CASP6 (caspase 6)
Description:
Cysteine protease that plays essential roles in programmed cell death, axonal degeneration, development and innate immunity. Acts as a non-canonical executioner caspase during apoptosis: localizes in the nucleus and cleaves the nuclear structural protein NUMA1 and lamin A/LMNA thereby inducing nuclear shrinkage and fragmentation. Lamin-A/LMNA cleavage is required for chromatin condensation and nuclear disassembly during apoptotic execution. Acts as a regulator of liver damage by promoting hepatocyte apoptosis: in absence of phosphorylation by AMP-activated protein kinase (AMPK), catalyzes cleavage of BID, leading to cytochrome c release, thereby participating in nonalcoholic steatohepatitis. Cleaves PARK7/DJ-1 in cells undergoing apoptosis (By similarity). Involved in intrinsic apoptosis by mediating cleavage of RIPK1. Furthermore, cleaves many transcription factors such as NF-kappa-B and cAMP response element-binding protein/CREBBP. Cleaves phospholipid scramblase proteins XKR4 and XKR9 (By similarity). In addition to apoptosis, involved in different forms of programmed cell death. Plays an essential role in defense against viruses by acting as a central mediator of the ZBP1-mediated pyroptosis, apoptosis, and necroptosis (PANoptosis), independently of its cysteine protease activity. PANoptosis is a unique inflammatory programmed cell death, which provides a molecular scaffold that allows the interactions and activation of machinery required for inflammasome/pyroptosis, apoptosis and necroptosis. Mechanistically, interacts with RIPK3 and enhances the interaction between RIPK3 and ZBP1, leading to ZBP1-mediated inflammasome activation and cell death. Plays an essential role in axon degeneration during axon pruning which is the remodeling of axons during neurogenesis but not apoptosis (By similarity). Regulates B-cell programs both during early development and after antigen stimulation (By similarity). (Microbial infection) Proteolytically cleaves the N protein of coronaviruses such as MERS-CoV and SARS-CoV. The cleavage of MERS-CoV N-protein leads to two fragments and modulates coronavirus replication by regulating IFN signaling. The two fragments produced by the cleavage interact with IRF3 inhibiting its nuclear translocation after activation and reduce the expression of IFNB and IFN-stimulated genes. The same mechanism seems to be used by other coronaviruses such as SARS-CoV and SARS-CoV-2 to enhance their replication.
Synonyms: CSP-6; MCH2; caspase-6
Tractability: Small molecule: a drug acting on it is in phase 2 or 3 trials; a structure with a bound ligand is known; a high-quality ligand is known; it has a high-quality binding pocket; it belongs to a druggable protein family. PROTAC: ubiquitination databases record sites on it; its protein half-life has been measured; a small molecule that binds it is known.
Target class: Cysteine protease; Protease; Cysteine protease CD clan; Enzyme; Cysteine protease C14 family
Gene: Protein-coding gene on chromosome 4 (109,688,622 to 109,703,583, reverse strand). Ensembl gene ENSG00000138794.
Subcellular location: Cytoplasm; Nucleus
Subcellular location (Human Protein Atlas): Cytosol; Nucleoli fibrillar center; Nucleoplasm
Pathways (Reactome):
Programmed Cell Death: Apoptotic cleavage of cellular proteins; Breakdown of the nuclear lamina; Caspase-mediated cleavage of cytoskeletal proteins
Gene Ontology:
Molecular function: cysteine-type endopeptidase activity; identical protein binding; protein binding; cysteine-type peptidase activity; endopeptidase activity
Biological process: activation of innate immune response; cellular response to staurosporine; epithelial cell differentiation; hepatocyte apoptotic process; positive regulation of apoptotic process; positive regulation of necroptotic process; protein autoprocessing; proteolysis; pyroptotic inflammatory response; regulation of programmed cell death; apoptotic process; positive regulation of neuron apoptotic process; protein maturation
Cellular component: cytoplasm; cytosol; fibrillar center; nucleoplasm; nucleus
Genetic constraint (gnomAD): Loss-of-function variants: 19 observed, 29.26 expected, observed/expected ratio (o/e) 0.65, 90% interval 0.45 to 0.95. The upper end of that interval is the gene's LOEUF score, 0.95, which puts it in group 4 of 6, group 1 being the genes least tolerant of losing a copy. Missense variants: 311 observed, 349.65 expected, observed/expected ratio (o/e) 0.89, 90% interval 0.81 to 0.98. Synonymous variants: 123 observed, 125.35 expected, observed/expected ratio (o/e) 0.98, 90% interval 0.85 to 1.14.
Homologues: Orthologues: chimpanzee CASP6 (99% identical), macaque CASP6 (97% identical), dog CASP6 (90% identical), rabbit CASP6 (88% identical), pig CASP6 (85% identical), mouse Casp6 (85% identical), rat Casp6 (84% identical), guinea pig CASP6 (72% identical), zebrafish casp6a (66% identical), tropical clawed frog casp6 (65% identical), zebrafish casp6b.1 (52% identical), zebrafish casp6b.2 (50% identical), and 5 more. Paralogues in human: CASP3 (35% identical), CASP7 (33% identical), CASP10 (32% identical), CASP8 (31% identical), CASP9 (30% identical), CASP2 (25% identical), CASP1 (24% identical), CASP14 (24% identical), CASP5 (23% identical), CASP4 (22% identical), CFLAR (21% identical), CASP12 (20% identical), and 4 more.
Diseases named in the same sentence as CASP6 in open-access papers:
CASP6 is named in the same sentence as 129 diseases in open-access papers, as found by Europe PMC text mining. Sharing a sentence is not in itself a finding about the gene and the disease. The quoted sentences say what the papers report.
Alzheimer disease (31 papers, 2012 to 2026). A progressive, neurodegenerative disease characterized by loss of function and death of nerve cells in several areas of the brain leading to loss of cognitive function such as memory and language. "Caspase-6 is extensively expressed in the brain and is associated to neurological disorders such as Alzheimer disease (AD) and HD, where it also seems to have therapeutic potential." (PMID 38824481, 2024). "Caspase-6 has been shown to be implicated in neurodegenerative conditions including Huntington’s and Alzheimer’s diseases; p62 droplets based autophagy is key to clearance of toxic aggregation-prone proteins." (PMID 34862482, 2022). "Caspase-6 (Casp6), a cysteine protease that cleaves its protein substrates after an aspartic acid residue, is associated with Alzheimer disease (AD) pathogenesis." (PMID 34135352, 2021). "Excess neuronal active Casp6 is associated with Alzheimer disease (AD) neuropathology and age-dependent cognitive impairment." (PMID 30940883, 2019). "The excess neuronal activity of Caspase-6 is associated with Alzheimer disease neuropathology and age-dependent cognitive impairment." (PMID 30940883, 2019). "Activated Caspase-6 (Casp6) is associated with age-dependent cognitive impairment and Alzheimer disease (AD)." (PMID 31843022, 2019). "Caspase-6 has also been associated with different models of neurodegeneration, such as Alzheimer’s disease." (PMID 30486235, 2018). "The activation of the aspartate-specific cysteinyl protease, Caspase-6, is proposed as an early pathogenic event of Alzheimer disease (AD) and Huntington’s disease." (PMID 28241839, 2017). "Caspase-6 (Casp6) is implicated in Alzheimer disease (AD) cognitive impairment and pathology." (PMID 34135352, 2021). "Caspase-6 is implicated in ND, including Huntington’s and Alzheimer’s diseases." (PMID 28025335, 2016). "A protease of interest, caspase-6, is a member of the apoptotic family of caspases, and has been shown to be involved in human neurodegenerative diseases such as Alzheimer’s disease and Parkinson’s disease." (PMID 41270077, 2025). "Previous studies have shown casp-6 involvement in neurodegeneration in the context of Alzheimer’s Disease." (PMID 41270077, 2025). "Tau cleaved at known casp-6 cleavage sites as well as active casp-6 are present in the brains of deceased Alzheimer’s Disease and frontotemporal dementia patients." (PMID 41270077, 2025). "According to the disease alliance terms, ENO1, CASP6, HSPD1, and CASP3 are associated with Alzheimer’s disease." (PMID 38107644, 2023). "Active Caspase-6 (Casp6) and Tau cleaved by Casp6 at amino acids 402 (Tau∆D402) and 421 (Tau∆D421) are present in early Alzheimer disease intraneuronal neurofibrillary tangles, which are made primarily of filamentous Tau aggregates." (PMID 33649324, 2021). "These include Caspase-6 (CASP6) whose proteolytically processed form has been shown to increase in correlation with amyloid beta pathologies in Alzheimer’s disease patients." (PMID 34379632, 2021). "Recent research has suggested that Casp6 mediates innate immunity and inflammasome activation and it is related to axonal degeneration and cognitive impairment in Alzheimer's disease (AD)." (PMID 34938813, 2021). "The genes associated with Alzheimer’s disease were Erb-B2 receptor tyrosine kinase 2 (ERBB2), Cystatin B (CSTB), and Caspase 6 (CASP6)." (PMID 34379632, 2021). "The cysteine protease Caspase-6 (Casp6) is a potential therapeutic target of Alzheimer Disease (AD) and age-dependent cognitive impairment." (PMID 29535332, 2018). "The role of caspase-6 has been intensively studied in the pathogenesis of neurodegenerative diseases such as Alzheimer's disease and Huntington’s disease." (PMID 28686630, 2017). "Caspase-6 has yet received thorough attention in the field of neurodegenerative diseases to understand the pathogenesis of Huntingon’s and Alzheimer’s diseases for achieving novel therapeutic strategies." (PMID 28686630, 2017).
Alzheimer disease (continued). "Proteins central to neurodegenerative diseases, such as Htt in HD, as well as amyloid precursor protein (APP), tau, and presenilin in Alzheimer’s disease (AD) are all caspase-6 substrates." (PMID 26505998, 2015). "Active Caspase-6 (Casp6) is considered a novel therapeutic target against Alzheimer disease (AD) since it is present in AD pathological brain lesions, associated with age-dependent cognitive decline, and causes age-dependent cognitive impairment in the mouse brain." (PMID 25470254, 2014). "Casp6 is also highly activated in neuritic plaques, neuropil threads, and neurofibrillary tangle lesions present in sporadic and familial forms of Alzheimer Disease (AD)." (PMID 25470254, 2014). "The active form of Casp6 and Tau cleaved by Casp6 (TauΔCasp6) are present in the three major neuropathological hallmarks of Alzheimer's disease: neuropil threads, neuritic plaques and neurofibrillary tangles in sporadic and familial forms of AD." (PMID 24265764, 2013). "The low levels of Caspase-6 in fetal and adult brain indicate that increased expression as observed in Alzheimer Disease is a pathological condition." (PMID 24265764, 2013). "Caspase-6 (casp-6), is a member of the apoptotic family of caspases (cysteine aspartic proteases) and has been shown to be involved in several neurodegenerative diseases, including Alzheimer's disease." (PMID 42308231, 2026). "Additionally, colocalization of active casp-6 with phospho-tau suggests a possible correlation between these two Alzheimer’s Disease hallmarks." (PMID 41270077, 2025). "Amyloid-β (Aβ), a peptide implicated in Alzheimer's disease, was shown to cause specific fragmentation of lamin proteins, which was mediated by an unidentified protease named nuclear scaffold protease (NSP) independently of caspase-6." (PMID 33145443, 2020). "The reactivation of Casp6 was found to have a strong correlation to cell death and specific roles in the CNS, especially in the case of neurodegenerative disorders such as axonal degeneration and Alzheimer's disease." (PMID 32831862, 2020). "Our results indicate that Caspase-6-mediated damage is reversible months after the onset of cognitive deficits and suggest that methylene blue could benefit Alzheimer disease patients by reversing Caspase-6-mediated cognitive decline." (PMID 31843022, 2019). "Indeed, caspase-6 upregulation has been reported in other neurodegenerative diseases involving protein aggregation, including Huntington’s Disease (HD) and Alzheimer’s Disease (AD)." (PMID 31682229, 2019). "In this context caspase-6 dependent mechanisms were shown to contribute for the exacerbation of neuronal lesions during Huntington’s disease and are critical during the axonal degeneration in the pathogenesis of Alzheimer's disease." (PMID 28686630, 2017). "Casp6 appears to play a major role in Alzheimer Disease (AD) pathogenesis." (PMID 24265764, 2013). "Moreover, active CASP6 is thought to be a potential therapeutic target against Alzheimer’s disease." (PMID 34226539, 2021). "In other pathways, caspase-6 is also known to cleave cytoskeletal and structural proteins, such as the microtubule-associated protein tau and amyloid precursor protein (APP), and caspase-6 is detected in neurodegenerative diseases, such as Alzheimer's disease and Huntington's disease." (PMID 22363841, 2012). "Moreover, caspase-6 has been implicated in a range of non-viral diseases, with dysregulated caspase-6 activity linked to conditions such as non-alcoholic steatohepatitis, Alzheimer’s disease, Huntington’s disease, and preeclampsia." (PMID 40920846, 2025). "Caspase-6-mediated cleavage of mutant huntingtin protein and amyloid precursor protein (APP) is critical for the onset of Huntington’s disease and Alzheimer’s disease respectively." (PMID 28659495, 2017). "Caspase-6 is an effector caspase that has not been investigated thoroughly despite the fact that Caspase-6 is strongly activated in Alzheimer disease brains." (PMID 24265764, 2013).
Huntington disease (16 papers, 2011 to 2025). Huntington disease (HD) is a rare neurodegenerative disorder of the central nervous system characterized by unwanted choreatic movements, behavioral and psychiatric disturbances and dementia. "Caspase-6 is a cysteinyl protease implicated in neurodegenerative conditions including Alzheimer's and Huntington's disease making it an attractive target for therapeutic intervention." (PMID 22253931, 2012). "This role of caspase-6 may have disease relevance as caspase-6 has been linked to Alzheimer’s and to Huntington’s disease." (PMID 35281082, 2022). "Caspase-6 has also been proposed to be involved in the cleavage of neurodegenerative disease-related proteins, such as huntingtin in Huntington’s disease (HD)." (PMID 26505998, 2015). "Caspase-6 is also thought to play a role in Huntington's disease as it mediates cleavage of mutant huntingtin protein to induce pathogenesis in relevant disease models." (PMID 22253931, 2012). "Aberrant activation of caspase-6 has recently emerged as a major contributor to the pathogeneses of neurodegenerative disorders such as Alzheimer's and Huntington disease." (PMID 22140457, 2011). "Whether caspase-6 contributes to vascular disease, as it does to neurodegenerative disorders such as Alzheimer’s, Parkinson’s, and Huntington’s disease, where cleavage of cytoskeletal proteins contributes to axonal degeneration, remains to be determined." (PMID 41227316, 2025). "It occurs by caspase-6 and -1 activity in both normal brain and Huntington’s disease brains." (PMID 34066037, 2021). "Moreover, activated caspase 6 was detected in human patient brains of Alzheimer and Huntington diseases long before cell death, highlighting a critical role in regulating caspase activity in both diseases." (PMID 26540204, 2015). "Caspase-6 has garnered much attention recently since it has been shown that it is involved in the developmental pruning of axons, and it has been suggested that similar pathways might erroneously be activated in neurodegenerative disorders such as Alzheimer's (AD) and Huntington disease (HD)." (PMID 22140457, 2011).
Cognitive impairment (15 papers, 2015 to 2024). Abnormal cognition is characterized by deficits in thinking, reasoning, or remembering. "Caspase-6 inhibitors reverse the cognitive impairment caused by caspase-6 overexpression and loss of caspase-6 reduces other disease aspects in a mouse model of Huntington’s." (PMID 35281082, 2022). "Taking into consideration that active Casp6 is associated with AD and cognitive impairment, it is tempting to speculate that CASP6 SNPs described in this study could be associated with decreased risk of age-related Casp6-mediated neurodegeneration." (PMID 29535332, 2018). "Expression of a self-activated form of Casp6 in mouse hippocampal CA1 neurons induces age-dependent cognitive impairment." (PMID 36220815, 2022). "Transgenic expression or injection of active human Casp6 (hCasp6) in mouse CA1 neurons is sufficient to induce age-dependent cognitive impairment, synaptic transmission deficits, neuroinflammation, and neurodegeneration, but does not generate NFT12,36,37." (PMID 33649324, 2021). "This contrasts with the ACL/G mice, and suggests that the higher and diversified expression of Casp6 in ACL/G brains exacerbates cognitive deficits." (PMID 31843022, 2019). "This study assessed if methylene blue (MB), a phenothiazine that inhibits caspases, alters Caspase-6-induced neurodegeneration and cognitive impairment in mice." (PMID 31843022, 2019). "Our results show that MB reversed Casp6-induced episodic and spatial memory impairment, when administered 3 to 4 months after the onset of cognitive deficits, which occur at 15 months of age." (PMID 31843022, 2019). "A preliminary study indicated that the treatment of Casp6 transgenic mice with the NWL-117 caspase peptide inhibitor reverses cognitive deficits." (PMID 31843022, 2019). "Mice expressing human Caspase-6 in hippocampal CA1 neurons develop age-dependent cognitive deficits, neurodegeneration and neuroinflammation." (PMID 31843022, 2019). "Most importantly, MB has the ability to reverse Casp6-mediated cognitive deficits, neurodegeneration and neuroinflammation." (PMID 31843022, 2019). "The ability of MB, a caspase inhibitor to inhibit Casp6 and reverse Casp6-mediated cognitive impairment, neuronal function, and inflammation was assessed after 1 month of treatment." (PMID 31843022, 2019). "The effect of inhibitors on age-dependent cognitive deficits in Caspase-6 transgenic mice was assessed by the novel object recognition task." (PMID 28241839, 2017). "Caspase 6 activation has been reported in hippocampus and cerebral cortex of cases of mild cognitive impairment, and of familial and sporadic AD." (PMID 25910195, 2015). "Overexpression of caspase-6 leads to cognitive deficits and astrocyte activation in aged mice, while inhibition of caspase-6 by methylene blue restores cognition function after the onset of cognitive deficits." (PMID 39122454, 2024). "Caspase 6 is related to cognitive impairment and inflammation in the brain." (PMID 36266523, 2023). "The re-establishment of the hippocampal intrinsic network by MB could thus reverse Casp6-mediated cognitive impairment." (PMID 31843022, 2019). "Therefore, methylene blue reverses Caspase-6-induced cognitive deficits by inhibiting Caspase-6, and Caspase-6-mediated neurodegeneration and neuroinflammation." (PMID 31843022, 2019). "This study demonstrates that Casp6-induced cognitive deficits, neuritic degeneration, and neuroinflammation are reversible and implies that human Casp6-dependent cognitive decline in AD may be prevented with a Casp6 inhibitor." (PMID 31843022, 2019). "The goal of this study was to investigate whether MB could reverse Casp6-mediated cognitive deficits, neurodegeneration, and neuroinflammation in mice overexpressing human Casp6." (PMID 31843022, 2019). "Consequently, Nlrp1, Casp1, and Casp6 represent feasible therapeutic targets against age-dependent cognitive deficits and AD." (PMID 30254377, 2018).